INS (insulin)
Diseases named in the same sentence as INS in open-access papers (continued):
Sharing a sentence is not in itself a finding about the gene and the disease.
gestational diabetes (continued). "Focusing on gestational diabetes mellitus (GDM), on one side, those women with GDM, especially when requiring insulin for treatment, have been found to have greater plasma levels of oxidative stress during the whole pregnancy in comparison to pregnant women without GDM." (PMID 36421415, 2022). "Gestational diabetes mellitus (GDM) is a disease in which pregnant women who did not have diabetes before pregnancy develops glucose intolerance because of the interference of pregnancy hormones with the action of insulin." (PMID 34616766, 2021). "The study also shows what the hormonal balance (insulin and IGF-1) looks like in women with a physiological course of pregnancy (without gestational diabetes), while most insulin and IGF-1 studies are conducted in women with gestational diabetes." (PMID 34371854, 2021). "This index was positively associated with HOMA B (p = 6.1 × 10−5) but not directly with gestational diabetes (p = 0.6), HOMA S (p = 0.2) or the insulin disposition index (p = 0.4)." (PMID 31087162, 2019). "However, whilst some guidelines allow for the use of noninsulin antidiabetic agents for gestational diabetes, the recommended treatment for preexisting T2DM during pregnancy is insulin." (PMID 34953068, 2022). "However, two weeks of CPAP use in women with gestational diabetes and OSA did not improve glucose levels but raised the insulin secretion in those adherents to CPAP." (PMID 35273777, 2022). "Furthermore, PRL stimulates β-cell proliferation, survival, and insulin production and pregnant mice lacking PRL receptors in β-cells develop gestational diabetes." (PMID 33746901, 2021). "In conclusion, GPC-4 levels rose significantly during pregnancy, correlated negatively with fasting insulin and HOMA-IR but might not be related to gestational diabetes mellitus status." (PMID 34903856, 2021). "Gestational diabetes mellitus (GDM) is diagnosed when maternal fasting and/or postprandial plasma glucose exceeds normal levels, yet adverse perinatal outcomes have been observed to occur along a spectrum of insulin and glucose levels in pregnancy, even in the absence of overt GDM." (PMID 32041106, 2020). "Gestational diabetes mellitus (GDM) represents any degree of glucose intolerance with onset during pregnancy, regardless of whether treated by insulin or diet modification, or whether the condition persists after pregnancy or not." (PMID 32972433, 2020). "However, the definition of “gestational diabetes” used in various studies investigating the trends of GDM fails to specify whether the patient requires dietary regulation alone or treatment with dietary regulation and insulin." (PMID 26292282, 2015).
prediabetes (988 papers, 2001 to 2026). "Prediabetes is increasingly recognized as a risk factor for sarcopenia, driven by chronic low-grade inflammation, insulin resistance, and impaired anabolic signaling." (PMID 42123593, 2026). "In the prediabetes group, two subtypes were identified: the Insulin-Deficient Prediabetes (IDPD) phenotype, comprising 66%, and the Insulin-Resistant Prediabetes (IRPD) phenotype, comprising 34% (Figure-1C-D)." (PMID 40678231, 2025). "Future studies should incorporate multiple diagnostic criteria, including OGTT, HbA1c, and insulin measurements, to provide a more accurate and comprehensive assessment of prediabetes." (PMID 41211213, 2025). "The review highlighted that these interventions contribute to DR reduction through improved insulin sensitivity, decreased inflammation, and weight loss, thereby preventing the transition from prediabetes to T2DM." (PMID 40563120, 2025). "Taken together, our findings highlight that short‐term training prior to clinically relevant weight loss is potentially able to improve brain insulin signaling among older adults with prediabetes." (PMID 39421964, 2025). "Sensitivity analyses were performed on a sample excluding patients with prediabetes to assess the impact of prediabetes; the association between age at menarche and fasting insulin remained significant with adjustment for model 4 (P for linear trend = .006)." (PMID 38912813, 2025). "Higher baseline eGFR predicted lower risk of incident prediabetes: hazard ratio 0.986 (95% confidence interval 0.975-0.997, P = .012), adjusted for age, sex, ethnicity, BMI, waist circumference, glucose, insulin sensitivity, insulin secretion, and albuminuria." (PMID 41163811, 2025). "Insulin-deficient subtypes made up a high proportion of T2D and prediabetes cases, harboring increased mortality hazards and excess years of life lost relative to normal glucose tolerance." (PMID 40678231, 2025). "In contrast, we highlight that the contributions to future T2D of longitudinal declines in insulin sensitivity were more associated with the progression to prediabetes and T2D than longitudinal decreases in beta-cell function." (PMID 41561051, 2025). "Insulin clamp tests have confirmed a progressive decline in islet β-cell function, even when glucose levels remain below the diagnostic threshold for prediabetes." (PMID 40162315, 2025). "A key strength lies in the ability to robustly evaluate insulin-deficient subtypes, particularly given their higher prevalence in this population, even at the prediabetes stage." (PMID 40678231, 2025). "IR is a hallmark of prediabetes and is characterized by an impaired cellular response to insulin stimulation at the peripheral tissues, such as skeletal muscle and adipose tissue." (PMID 38338783, 2024). "This is also true for high-risk patients, that is, patients already diagnosed with prediabetes, in whom a combination of decreased baseline insulin sensitivity and secretion appears to act additively to increase the risk for T2D development over time." (PMID 38957656, 2024). "Our data indicate that partial loss of ANP/GCA signaling specifically in skeletal muscle is sufficient to cause systemic insulin resistance and prediabetes under standard nutritional conditions." (PMID 39383215, 2024). "Reduced insulin sensitivity has been shown to confer a risk to developing prediabetes in the pediatric population." (PMID 39726936, 2024). "Others suggest that HbA1c-defined prediabetes is associated with a defective insulin response in combination with inappropriate suppression of glucagon." (PMID 38397965, 2024). "Mice fed a WD for 1 month displayed increased beta cell [Ca2+]i dynamics linked to enhanced insulin secretion as a functional compensatory mechanism in prediabetes." (PMID 38814444, 2024). "A previous study showed low circulating 25-hydroxyvitamin D concentrations are associated with defects in insulin action and insulin secretion in people with prediabetes." (PMID 39682344, 2024).
prediabetes (continued). "Individuals in the MIDD subgroup had a low risk burden equivalent to prediabetes, but with reduced insulin secretion." (PMID 39136497, 2024). "We further demonstrate that partial loss of ANP/GCA signaling specifically in skeletal muscle is sufficient to cause systemic insulin resistance and prediabetes." (PMID 39383215, 2024). "In our study, we found that prediabetes was associated with a smaller total and trabecular area, as was a lower insulin sensitivity." (PMID 39108361, 2024). "In prediabetes, a low adherence to a specific dietary pattern (1 and 2) was associated with lower fasting plasma glucose, blood pressure and serum insulin, compared to increased adherence." (PMID 37110190, 2023). "The low production of SCFAs is associated with alterations in insulin sensitivity and inadequate immune system modulation, which are risk factors for prediabetes and T2D." (PMID 37441494, 2023). "In prediabetic obese mice, virally induced IFN-γ (using murine cytomegalovirus) drives the progression from prediabetes to T2D by causing insulin resistance in skeletal muscles through downregulation of the insulin receptor." (PMID 36262060, 2023). "Impaired fasting glucose is one of diagnostic criteria for prediabetes and closely related to changes in β cell glucose sensitivity and liver insulin sensitivity." (PMID 37238375, 2023). "We aimed to explore the effects of Aβ on insulin action and insulin secretion in vitro and the association of plasma Aβ with prediabetes in human." (PMID 37538787, 2023). "It has been shown that genotypes predisposing to prediabetes are associated with beta-cell function and insulin secretion." (PMID 35190847, 2022). "In patients with prediabetes, decreased thyroid function has been associated with decreased insulin sensitivity." (PMID 36114679, 2022). "There are very few well-designed intervention trials investigating the role of magnesium supplementation in the improvement of metabolic profile and insulin sensitivity in the people with prediabetes as a high risk group to develop diabetes." (PMID 36307427, 2022). "Systemic hyperinsulinaemia (a hallmark of prediabetes), as a result of insulin hypersecretion from the beta‐cell, promotes weight gain due to the systemic anabolic functions of insulin." (PMID 36056607, 2022). "IR is a key risk factor of metabolic dysfunction in prediabetes and T2D, characterized by deterioration in tissue sensitivity to insulin and a compensatory increase in insulin secretion." (PMID 36355827, 2022). "In conclusion, given its high prevalence, prediabetes and subsequent dysregulation of insulin secretion causing transient hypoglycemia is the most likely cause of the TLOC in our patient." (PMID 33952305, 2021). "For example, a zoom-in on the entity glucose reveals the entities prediabetes, glucose tolerance test, homeostatic process, HbA1c, insulin, or beta-cells as key entities associated with the groups at risk to COVID-19." (PMID 34395368, 2021). "This investigation included 13 studies to evaluate the effect of RT, AET, AET + RT, and CT interventions on five indicators (BMI; HOMA-IR; and FBG, HbA1c, and insulin levels) to evaluate prediabetes risk reduction using direct and network meta-analyses." (PMID 34488728, 2021). "Several studies have demonstrated that the risk of getting prediabetes increases with age due to a decrease in insulin secretion with advancing age." (PMID 33546150, 2021). "Dietary sodium restriction should be considered, but a deficient sodium intake (to less than 1.5–2.0 g/day) carries the risk of hyponatremia, leading to reduced insulin sensitivity and prediabetes." (PMID 34444908, 2021). "Myocardial triglyceride content is associated with insulin sensitivity and is increased in prediabetes." (PMID 34827678, 2021). "This study aimed to investigate the correlation between proinsulin (PI), true insulin (TI), PI/TI, 25(OH) D3, waist circumference (WC), and risk of prediabetes." (PMID 32881889, 2020).
prediabetes (continued). "In order to evaluate which VAT-related index has the best diagnostic performance to prognosticate insulin sensitivity and prediabetes, univariate linear correlation analyses were performed." (PMID 32664590, 2020). "Insulin sensitivity and β-cell function can be improved by weight loss to prevent prediabetes into T2DM." (PMID 31214029, 2019). "According to the investigators of the study, vitamin D supplementation in persons with prediabetes and an inadequate vitamin D status or a vitamin D deficiency can improve insulin sensitivity and slow metabolic deterioration." (PMID 31689953, 2019). "To date, several studies confirmed the central role played by IR in enhancing the CVD risk in prediabetes and insulin-resistant individuals, with a relative risk approximately twice higher than non-insulin resistant subjects." (PMID 30832662, 2019). "For example, our group recently showed that APP/PSEN1 amyloid-depositing mice exhibit reduced hypothalamic insulin signaling and are more susceptible to aging and over-nutrition induced prediabetes." (PMID 29945658, 2018). "This evidence is supported by the inverse and significant relationship between OPN levels and plasma glucose profiles and insulin sensitivity, suggesting a potential combined role in the glucose homeostasis abnormalities underlying prediabetes." (PMID 29151224, 2018). "Prediabetes has been associated with a 40% reduction in whole-body insulin sensitivity, substantial decline in glucose sensitivity of β cells, and increased waist circumference and BMI when compared with normal glucose tolerance." (PMID 30513818, 2018). "In prediabetes, β-cell volume is already lost for 30–40% and this alteration is associated with a progression of insulin resistance to increased insulin demand." (PMID 29052766, 2018). "Vitamin D has shown to have effects on insulin secretion and action and in both pediatric and adult studies an inverse association between vitamin D levels and development of prediabetes and/or T2DM have been demonstrated." (PMID 29641737, 2018). "Earlier reports have proposed reduced granular priming as the cause of reduced first‐phase insulin secretion during prediabetes." (PMID 29122960, 2017). "Two dynamic features of insulin secretion have been implicated in postprandial glycemic control in prediabetes and type II diabetes (T2D)." (PMID 29118381, 2017). "Our data represent a step towards understanding the mechanisms that underlie increased insulin secretion in prediabetes and show that, in addition to an expansion in cell numbers, functional changes are occurring in the beta cell." (PMID 27048248, 2016). "Hyperthyroid individuals have an increased insulin secretion and higher free triiodothyronine levels are specifically associated with improved insulin secretion in individuals with prediabetes." (PMID 27686165, 2016). "Age independently affected insulin secretion, resulting in a relative risk for prediabetes of 2.95 (95%CI 1.38–4.83) with a cut-off at 48 years." (PMID 26398489, 2015). "IR is a hallmark of prediabetes and can result from proinflammatory cytokines such as TNFα and IL1β causing impaired insulin signaling in insulin target organs." (PMID 26317345, 2015). "The prediabetes itself is associated with both insulin- and glucose resistance, decreased insulin sensitivity, and decreased beta-cell function." (PMID 21122092, 2010). "On the other hand, we found that insulin is a significant predictor of serum testosterone (b = 0.07, t = 2.1, p = 0.04, 95% CI [0.003 – 0.13]), and higher insulin levels are associated with higher levels of testosterone in the prediabetes group." (PMID 41384021, 2025). "These genetic variants may be indicative of IR and abnormal insulin secretion, holding promise as potential biomarkers for prediabetes prevention." (PMID 40162315, 2025).
prediabetes (continued). "Aging and prediabetes have been linked to declines in insulin transport to brain regions, thereby raising questions on the impact peripheral insulin may have in ADRD pathogenesis." (PMID 39421964, 2025). "The inverse association between thyroid resistance and prediabetes aligns with evidence that reduced thyroid hormone action may lower hepatic gluconeogenesis and improve peripheral insulin sensitivity." (PMID 40600010, 2025). "A post hoc analysis of data from the Pathobiology of Prediabetes study in a bi-racial cohort showed that baseline HSI was associated with insulin sensitivity (r = −0.44, p < 0.0001), high-sensitivity C-reactive protein (r = 0.37, p < 0.0001) and adiponectin (r = −0.24, p < 0.0001)." (PMID 40642238, 2025). "These compounds may exert antioxidant, anti-inflammatory, or insulin-sensitizing effects, which could underlie the associations we observed between coffee intake and lower odds of prediabetes and T2DM." (PMID 40836180, 2025). "Positive correlation of insulin with testosterone, antral follicle count, and ovarian volume being only found in prediabetes group suggested that prediabetes might render ovaries susceptible to the PCOS-like changes." (PMID 41384021, 2025). "Consequently, as the global incidence of prediabetes escalates, it becomes imperative to elucidate the underlying mechanisms that contribute to insulin resistance and metabolic dysregulation." (PMID 40806101, 2025). "Moreover, an uncoordinated [Ca2+]i signal associated with insulin hypersecretion was demonstrated to be an early sign of prediabetes." (PMID 38814444, 2024). "In other words, the disruption of the circadian clock due to skipping breakfast may affect insulin secretion and other factors, causing an increase in postprandial blood glucose, leading to an increase in HbA1c, i.e., the risk of prediabetes." (PMID 36909337, 2023). "Findings from both our study and that in prediabetes suggest that adhering to TRE may enhance insulin sensitivity and β-cell responsiveness in prediabetes patients, potentially reducing the risk of progression to DM for these individuals." (PMID 37836517, 2023). "Waist circumference could potentially be used as a clinical equivalent for visceral adipose tissue, which impairs insulin sensitivity and predisposes to prediabetes when excessive." (PMID 36294218, 2022). "Isocaloric TRF may improve fasting insulin levels independently of weight loss, especially in those who are prediabetes." (PMID 33849562, 2021). "Participants with decreased central sensitivity of thyroid hormones tended to have increased FT4 levels, which may decrease risk of prediabetes by improving insulin sensitivity and glucose utilization." (PMID 34017311, 2021). "Furthermore, sugar-sweetened beverage consumption has been positively associated with prediabetes and inversely with insulin sensitivity in observational studies." (PMID 31486878, 2020). "Expert opinion: Insulin sensitivity and β-cell function could be improved by weight loss to prevent prediabetes into T2DM." (PMID 31214029, 2019). "For public health advice, it is interesting to know if a more plant-based and less animal-based diet may also influence insulin resistance and risk of prediabetes and T2D beyond strict adherence to a vegetarian or vegan diet." (PMID 29948369, 2018). "Next, among many candidate SNPs have been proposed to be associated with T2D and prediabetes, the present study was only interested in 5 SNPs in genes related to insulin pathway, and thereby the studied genetic variant had a small effect on prediabetes despite statistical significance." (PMID 26334876, 2015). "One may therefore speculate that the genetic risk for prediabetes is mediated mainly through the genetic variation affecting insulin secretion." (PMID 22768041, 2012).